CFTR (CF transmembrane conductance regulator)
Diseases named in the same sentence as CFTR in open-access papers (continued):
Sharing a sentence is not in itself a finding about the gene and the disease.
pancreatitis (continued). "Pancreatitis must also be considered in the differential diagnosis for pancreatic sufficient and pancreatic insufficient CF patients on CFTR modulator therapies." (PMID 36678791, 2023). "This CFTR genotype–phenotype correlation found in pancreatitis is unique compared to other organ manifestations related to the complex monogenic nature of the CF disease." (PMID 36832409, 2023). "At least five genes have been identified to be associated with pancreatitis: serine protease 1 (PRSS1), serine peptidase inhibitor Kazal type 1 (SPINK1), CFTR, chymotrypsin C (CTRC), and calcium sensing receptor (CASR)." (PMID 35844741, 2022). "CFTR-related pancreatitis represents an illustrative approach to etiology-based disease management using highly targeted therapy." (PMID 36046477, 2022). "The genetic factors leading to pancreatitis have been studied extensively and several genes such as SPINK1, CFTR, HLA‐DRB*0401, and PRSS1 have been attributed with the increase in predisposition to develop pancreatitis." (PMID 35340657, 2022). "We therefore used a strain of transgenic mice with significant residual CFTR function (CFTRtm1HGU) to induce pancreatitis experimentally by serial caerulein injections." (PMID 33682322, 2021). "Several seminal studies published in the last decade point towards a prominent role of impaired CFTR-mediated HCO3− transport in the pathophysiology of pancreatitis." (PMID 35011616, 2021). "Recent studies indicate that CFTR function is not only compromised in genetic but also in selected patients with an acquired form of pancreatitis induced by alcohol, bile salts or smoking." (PMID 35011616, 2021). "Genetic factors including mutations in CFTR, PRSS1, SPINK1 genes play an important role among the causes of acute, recurrent pancreatitis." (PMID 33652736, 2021). "In transgenic mice with impaired Cl− transport but significant residual CFTR function (CFTRtm1HGU), the severity of cerulean-induced pancreatitis was increased, mostly via impairment of PDC function and a shift towards a pro-inflammatory phenotype." (PMID 35011616, 2021). "In view of the apparent relevance of HCO3− in the pathophysiology of CF and CFTR-related disorders (CFTR-RD) such as pancreatitis, it is perhaps surprising that most research into the function of CFTR has focused on its role as a Cl− channel." (PMID 35011616, 2021). "Although these model studies provide valuable insight into the course of CFTR function and expression during pancreatitis, species differences should be considered, not only in epithelial physiology but also in drug sensitivity." (PMID 35011616, 2021). "Germline testing, currently for recommended etiologic mutations associated with pancreatitis, includes evaluation for pathogenic variants in the CEL, CFTR, CPA1, CTRC, PRSS1, and SPINK1 genes in symptomatic individuals." (PMID 33375361, 2020). "In this cohort of CRMS/CFSPID infants, however, as many as 3 out of 26 patients in group A (11.5%) aged < 8 years showed episodes of pancreatitis and were classified as CFTR-RD." (PMID 33322690, 2020). "Thus, CFTR may also present as a genetic risk factor in paediatric pancreatitis in Japanese." (PMID 30992994, 2019). "Recent studies have suggested an important role for CFTR in the development of pancreatitis, particularly through its role in intraluminal pH regulation from bicarbonate secretion and the flushing of ductal proteins." (PMID 26100556, 2015). "Only SPINK1 N34S heterozygotes were used for trans-heterozygote analysis with CFTR, since homozygous SPINK1 N34S is sufficient to cause pancreatitis." (PMID 25033378, 2014). "In another study comparing incidence of CFTR mutations between patients with pancreatitis and controls undergoing ERCP, 22% of patients with pancreatitis and pancreas divisium had a CFTR mutation compared with 0% of controls with pancreas divisum." (PMID 18501000, 2008).
pancreatitis (continued). "Ursodeoxycholate, novel mitochondrial transition pore inhibitor N-methyl-4-isoleucine cyclosporin, inhibitors of TRPM2, kynurenic acid and its analog SZR-72, CFTR corrector (VX-661) and potentiator (VX-770), and fentanyl improved the outcome of pancreatitis in different experimental models." (PMID 40004893, 2025). "However, preliminary reports suggest potential benefit for patients with CFTR‐related pancreatitis, but reported benefits and risks are inconsistent." (PMID 40468859, 2025). "Additionally, pancreatitis diagnoses often occurred years after the CFTR carrier status was first documented, further complicating the recognition of this connection." (PMID 40468859, 2025). "Our experiments revealed that toxic substances that induce pancreatitis, such as alcohol, fatty acids, bile acids, and smoking induce toxic calcium signaling, mitochondrial damage, damage of the anion exchanger, and CFTR, and as a result severely inhibit fluid and bicarbonate secretion." (PMID 40004893, 2025). "In all 3 patients, mutations in CFTR and other pancreatitis-associated genes were excluded, indicating that no other known genetic background was likely to be implicated in their pancreatic presentations." (PMID 41312553, 2025). "However, the likelihood of being a CFTR carrier given an acute pancreatitis diagnosis was quite high; nearly one in seven patients with pancreatitis (14.1%)." (PMID 40468859, 2025). "In pancreatitis, both CFTR expression and function are severely impaired." (PMID 40004893, 2025). "Furthermore, some pancreatitis-related genes (i.e., CFTR) display complex inheritance patterns and low penetrance, such that identifying high risk patients for selective referrals for genetic testing is challenging." (PMID 39172977, 2024). "For example, oxidative stress from alcohol and smoking may exacerbate genetic mutations associated with pancreatitis, such as those in the SPINK1 and CFTR genes." (PMID 39221257, 2024). "Taken together, these findings suggest that drug therapies directed at improving CFTR function, or ductal anion and fluid secretion in general, may be applicable for management of pancreatitis in a wider population." (PMID 38262945, 2024). "In this manner, stimulation of CFTR activity could help to contain the progression of pancreatitis at an early stage, and limit tissue injury." (PMID 38262945, 2024). "Pancreatitis can manifest as a symptom of CF or CFTR-Related Disease." (PMID 38611676, 2024). "Another subset of patients treated with CFTR modulators are those with a recovered pancreatic function and who may develop pancreatitis (this fact suggests that treatment could increase pancreatic acinar reserve)." (PMID 36678791, 2023). "Interestingly, we found no mutations that passed quality control or the expected segregation pattern, in genes known to be associated with pancreatitis such as PRSS1, CFTR, SPINK, CPA1, CTRC, CLDN2, and PLINP." (PMID 36699452, 2022). "In addition, variations in the pancreatitis-related genes CFTR (8 cases [0.8%]) and SPINK1 (21 cases [2.1%]) were frequent in patients with PDAC." (PMID 35171259, 2022). "Non-CF-causing CFTR mutations are also included in experimental pancreatitis models and underline the essential role of CFTR function in PDC (patho-)physiology." (PMID 35011616, 2021). "This suggests a role for CFTR genotype testing in pancreatitis patients to identify those who could benefit from CFTR modulator therapy." (PMID 35011616, 2021). "As a second candidate gene for pancreatitis, CFTR was chosen for sequencing." (PMID 34768335, 2021). "Thus far, only a few studies have addressed the effectiveness of CFTR modulators in animal models of pancreatitis." (PMID 35011616, 2021). "A substantial body of evidence indicates that the loss of ductal CFTR-dependent fluid and HCO3− secretion may precipitate the development of pancreatitis." (PMID 35011616, 2021).
pancreatitis (continued). "CFTR modulators may decrease episodes of pancreatitis among individuals with CF with residual pancreatic function and significantly reduce pulmonary exacerbations even in patients without early lung function improvement." (PMID 33713579, 2021). "The D1270N mutation that is not CF-causing but alters bicarbonate preference of CFTR and can lead to pancreatitis is located on the surface of NBD2." (PMID 31978131, 2020). "In the future, treatment with CFTR correctors may offer an additional therapeutic tool to treat pancreatitis." (PMID 31614661, 2019). "While CFTR modulation has been shown to alkalinize the pH of the alimentary tract and potentially augment pancreatic enzyme activity, the effect of ivacaftor on recurrent pancreatitis is emerging." (PMID 31296159, 2019). "Tadashi Kaname, of Tokyo’s National Center for Child Health and Development, and colleagues sequenced the cystic fibrosis transmembrane conductance regulator gene (CFTR) in 28 Japanese children with pancreatitis of unknown origin." (PMID 30992994, 2019). "To further consolidate the possibility that CFTR function directly affects insulin secretion, we examined the cell–cell functional correlation between PDECs and islet cells derived from pancreatitis/CF patient, who was diagnosed with very mild CF and underwent TPIAT." (PMID 31311920, 2019). "All these cases were referred to the Adult Regional Reference Centre for CF, and seven out of eight were diagnosed with CFTR-RD for borderline sweat test and recurrent pancreatitis (three cases), diffuse bronchiectasis (three cases), and distal intestine obstructive syndrome (one case)." (PMID 31877800, 2019). "To better understand the location and structural effects of the nine amino acid variants conferring risk of pancreatitis and causing dysfunction of the electrophysiological response to WNK1-SPAK activation, we developed structural models of CFTR and conducted dynamic simulations." (PMID 25033378, 2014). "For example, most of the known gene mutations linked to pancreatitis, such as the serine protease inhibitor Kazal-type 1 (SPINK1) and cystic fibrosis transmembrane conductance regulator (CFTR), increase the likelihood of developing the disease, but do not appear to initiate it by themselves." (PMID 23185258, 2012). "In addition to PRSS1, CFTR, and SPINK1, the CTRC and CASR genes are additional risk factors that appear to increase risk of pancreatitis in the context of one of three primary susceptibility factors." (PMID 23230421, 2012). "The combination of pancreatic divisum and abnormal CFTR function may contribute to the severity and frequency of recurrent pancreatitis." (PMID 18501000, 2008). "It is possible that the combination of pancreas divisum and abnormal CFTR function may contribute to the severity and frequency of recurrent pancreatitis." (PMID 18501000, 2008). "CFTR mutations should be considered in cases of chronic or recurrent pancreatitis despite a negative sweat test and the presence of pancreas divisum." (PMID 18501000, 2008). "Overlooking CFTR status may lead to diagnostic delays, misaligned treatments, and potentially unnecessary procedures such as ERCP, which can increase complications or even trigger pancreatitis." (PMID 40468859, 2025). "While individuals carrying a single pathogenic CFTR variant do not develop classical CF, numerous population‐based studies suggest a modestly elevated risk of CF‐related phenotypes—most consistently pancreatitis—while effect sizes for respiratory conditions are small and sometimes nonsignificant." (PMID 40468859, 2025). "Additionally, pancreatitis is the second most common CFTR-related disorder (CFTR-RD)." (PMID 40332394, 2025). "Because CFTR mutations are not necessarily correlated with the onset of pancreatitis, PRSS1, SPINK1 and CTRC mutations may also lead to pancreatitis." (PMID 36835437, 2023).
pancreatitis (continued). "Given the well-studied role of CFTR in pancreatitis, it is likely that GC-C also plays a role in the development and progression of pancreatitis; however, whether the induction of GC-C during pancreatitis serves a protective or detrimental function remains unresolved." (PMID 35846281, 2022). "However, it is also believed that PD alone is not a risk factor for pancreatitis but has synergistic effects with genetic factors, especially CFTR gene mutations, which can promote the development of CP." (PMID 35958176, 2022). "Interestingly, the CFTR variant R75Q, which has selective bicarbonate transport defect, is associated with pancreatitis but not classical CF." (PMID 27382190, 2016). "Later, the effects of alcohol on ductal cell cystic fibrosis transmembrane conductance regulator (CFTR) were shown to promote acute pancreatitis; CFTR function was restored with a substance called orkambi to ameliorate the severity of pancreatitis." (PMID 40254129, 2026). "So far, several genes with potential application in the diagnosis of pancreatitis have been described, including PRSS1, CFTR, CTRC, and SPINK1." (PMID 39457082, 2024). "In addition to “classic CF”, pathogenic variants in the CFTR gene may also cause less severe CFTR-related disorders, such as CFTR-related pancreatitis and congenital bilateral absence of the vas deferens (CBAVD)." (PMID 39126101, 2024). "This review summarizes our current knowledge of the role of CFTR in pancreatic ductal fluid and HCO3− transport, and the role of CFTR dysfunction in pancreatitis." (PMID 35011616, 2021). "However, not all patients suffering from pancreatitis carry CFTR mutations, and not all CFTR mutations may be amenable to correction." (PMID 35011616, 2021). "The CFTR R117H variant was identified in 22 cases (2.3%) and 8 controls (0.7%) (p = 0.001), with only 3 cases and 1 control having the CF-associated R117H*T5 haplotype (p = ns), which links the CFTR variant R117H to pancreatitis regardless of the intron 8 T5 haplotype." (PMID 25033378, 2014). "Manual chart review revealed that CFTR carrier screening results were not clinically correlated with pancreatitis diagnoses." (PMID 40468859, 2025). "Pancreatitis is also a typical manifestation of CFTR-related disease, a range of disorders not meeting criteria for CF diagnosis, but with evidence for moderate CFTR dysfunction, and CF-like pathology often presenting in a single organ." (PMID 38262945, 2024). "The carriers of this variant with another mutation causing disease, have different clinical pictures, from total absence of symptoms to CFTR related disease (eg recurrent pancreatitis, azoospermia, isolated bronchiectasis)." (PMID 37420288, 2023). "However, in a retrospective administrative database study, the question that was asked (do CFTR modulators reduce the rate of initial attack of pancreatitis in patients al low individual risk) may not answer more specific patient questions needed to address a precision medicine approach." (PMID 36046477, 2022). "To experimentally recreate a situation closer to the human geno‐ and phenotype, we have studied experimental pancreatitis in a mouse strain (CFTRtm1HGU) with significant residual CFTR function and no spontaneous pancreatic phenotype before adulthood." (PMID 33682322, 2021). "We observed that the pancreatic ductal organoids showed partially impaired CFTR function (20% lower than non-CF pancreatitis patient in basal secretion and under 5.3% in FSK-stimulated secretion)." (PMID 31311920, 2019). "It would be worth assessing whether CFTR corrector and potentiator are also able to correct AQP1 expression in animal models of pancreatitis." (PMID 31614661, 2019). "The pancreatitis in this patient was not due to gallstones or alcohol abuse, and analysis of genes known to be associated with pancreatitis, such as SPINK1, CFTR, PRSS1 and CTRC, did not reveal any mutations." (PMID 26082470, 2015).
pancreatitis (continued). "Our study highlights a panel of individuals that may have been overlooked for CFTR dysfunction due to a nonpulmonary primary presentation, such as pancreatitis." (PMID 41536752, 2026). "While routine follow‐up may not be necessary for every CFTR carrier, a system that alerts clinicians to a patient's CFTR carrier status could be highly valuable when pancreatitis is diagnosed or suspected." (PMID 40468859, 2025). "Whereas severe mutations in CFTR cause fibrosis of the pancreas in utero, CFTR mutants with residual function, or CFTR variants with a normal chloride but defective bicarbonate permeability (CFTRBD), are associated with an enhanced risk of pancreatitis." (PMID 35011616, 2021). "Using in vitro models, human tissues and transgenic mice, we have shown that AQP1 plays essential role in ductal fluid and HCO3- secretion, lack of CFTR decreases its expression and deletion of AQP1 is strongly associated with increased susceptibility of the gland to pancreatitis." (PMID 30050452, 2018). "In addition, modulators were shown to rescue pancreatic function in a non-CF model of pancreatitis, indicating that they may also improve wild type CFTR function." (PMID 38262945, 2024). "To test whether the absence of a greater disease severity after one hour of pancreatitis was due to an acinar cell‐specific effect in CFTRtm1HGU mice, we isolated acini from the pancreas of CFTR‐disrupted and wild‐type animals and incubated them in parallel with CCK for up to 60 minutes." (PMID 33682322, 2021).